IL1RAP (interleukin 1 receptor accessory protein)
Description:
Coreceptor for IL1RL2 in the IL-36 signaling system (By similarity). Coreceptor with IL1R1 in the IL-1 signaling system. Associates with IL1R1 bound to IL1B to form the high affinity interleukin-1 receptor complex which mediates interleukin-1-dependent activation of NF-kappa-B and other pathways. Signaling involves the recruitment of adapter molecules such as TOLLIP, MYD88, and IRAK1 or IRAK2 via the respective TIR domains of the receptor/coreceptor subunits. Recruits TOLLIP to the signaling complex. Does not bind to interleukin-1 alone; binding of IL1RN to IL1R1, prevents its association with IL1R1 to form a signaling complex. The cellular response is modulated through a non-signaling association with the membrane IL1R2 decoy receptor. Coreceptor for IL1RL1 in the IL-33 signaling system. Can bidirectionally induce pre- and postsynaptic differentiation of neurons by trans-synaptically binding to PTPRD (By similarity). May play a role in IL1B-mediated costimulation of IFNG production from T-helper 1 (Th1) cells (Probable). [Isoform 2]: Associates with secreted ligand-bound IL1R2 and increases the affinity of secreted IL1R2 for IL1B; this complex formation may be the dominant mechanism for neutralization of IL1B by secreted/soluble receptors. Enhances the ability of secreted IL1R1 to inhibit IL-33 signaling (By similarity). [Isoform 4]: Unable to mediate canonical IL-1 signaling. Required for Src phosphorylation by IL1B. May be involved in IL1B-potentiated NMDA-induced calcium influx in neurons (By similarity).
Synonyms: IL-1RAcP; C3orf13; IL1R3
Tractability: Antibody: an approved drug acts on it; its Gene Ontology location is reachable by antibodies, with high confidence; UniProt places it where antibodies can reach, with medium confidence; UniProt predicts a signal peptide or a membrane-spanning region. PROTAC: ubiquitination databases record sites on it; its protein half-life has been measured.
Gene: Protein-coding gene on chromosome 3 (190,514,051 to 190,659,750, forward strand). Ensembl gene ENSG00000196083.
Subcellular location: Cell membrane (Isoform 1); Secreted (Isoform 2); Secreted (Isoform 3)
Subcellular location (Human Protein Atlas): Cytosol; Vesicles; Predicted to be secreted
Pathways (Reactome):
Immune System: Interleukin-1 signaling; Interleukin-33 signaling; Interleukin-36 pathway
Signal Transduction: PI5P, PP2A and IER3 Regulate PI3K/AKT Signaling; PIP3 activates AKT signaling
Neuronal System: Receptor-type tyrosine-protein phosphatases
Gene Ontology:
Molecular function: coreceptor activity; protein binding; interleukin-1 receptor activity; interleukin-33 receptor activity; NAD+ nucleosidase activity, cyclic ADP-ribose generating; signaling receptor activity
Biological process: interleukin-1-mediated signaling pathway; interleukin-33-mediated signaling pathway; positive regulation of canonical NF-kappaB signal transduction; positive regulation of MAPK cascade; cytokine-mediated signaling pathway; immune response; inflammatory response; microglial cell activation involved in immune response; monocyte differentiation; negative regulation of inflammatory response; negative regulation of interleukin-1 alpha production; negative regulation of interleukin-1 beta production; negative regulation of interleukin-1-mediated signaling pathway; positive regulation of cytokine production involved in inflammatory response; positive regulation of inflammatory response; positive regulation of synapse assembly; protein-containing complex assembly; positive regulation of interleukin-13 production; positive regulation of interleukin-4 production; positive regulation of interleukin-5 production; positive regulation of interleukin-6 production; regulation of postsynaptic density assembly; regulation of presynapse assembly; signal transduction; synaptic membrane adhesion; and 1 more
Cellular component: interleukin-1 receptor complex; membrane; receptor complex; cell surface; plasma membrane; extracellular region; glutamatergic synapse; synapse
Genetic constraint (gnomAD): Loss-of-function variants: 24 observed, 44.33 expected, observed/expected ratio (o/e) 0.54, 90% interval 0.39 to 0.76. The upper end of that interval is the gene's LOEUF score, 0.76, which puts it in group 3 of 6, group 1 being the genes least tolerant of losing a copy. Missense variants: 452 observed, 591.28 expected, observed/expected ratio (o/e) 0.76, 90% interval 0.71 to 0.83. Synonymous variants: 220 observed, 219.37 expected, observed/expected ratio (o/e) 1, 90% interval 0.9 to 1.12.
Homologues: Orthologues: mouse Il1rap (89% identical), chimpanzee IL1RAP (86% identical), macaque IL1RAP (85% identical), rabbit IL1RAP (81% identical), dog IL1RAP (79% identical), guinea pig IL1RAP (76% identical), rat Il1rap (76% identical), pig IL1RAP (54% identical), tropical clawed frog il1rap (54% identical). Paralogues in human: IL1RAPL2 (34% identical), IL1RAPL1 (34% identical), IL18R1 (26% identical), IL1RL1 (23% identical), IL18RAP (23% identical), IL1R1 (21% identical), IL1RL2 (21% identical), IL1R2 (14% identical), LAG3 (10% identical), SIGIRR (9% identical).
Diseases named in the same sentence as IL1RAP in open-access papers:
IL1RAP is named in the same sentence as 108 diseases in open-access papers, as found by Europe PMC text mining. Sharing a sentence is not in itself a finding about the gene and the disease. The quoted sentences say what the papers report.
leukemia (14 papers, 2012 to 2025). A malignant (clonal) hematologic disorder, involving hematopoietic stem cells and characterized by the presence of primitive or atypical myeloid or lymphoid cells in the bone marrow and the blood. "For example, because IL1 receptor-associated protein (IL1RAP) is a tumor-associated antigen on cell surface, targeting this antigen was attempted to eradicate leukemia stem cells, but several issues of toxicity and side effects were associated with its lack of specificity." (PMID 38741123, 2024). "In leukaemia, IL1RAP is prominently expressed on the surface of leukaemia stem cells, where it drives cell proliferation and survival via activation of the IL-1 signalling pathway." (PMID 40444099, 2025). "Prior research has indicated that IL1RAP can be targeted therapeutically to eliminate leukemia; however, the blocking activity of certain IL1RAP antibodies is ineffective in the context of FLT3-ITD." (PMID 40229904, 2025). "Among the genes with significant changes upon TMIGD2 depletion were factors closely associated with cell-cycle (CDKN1A and CCND1) and leukemia stemness (CD93 and IL1RAP)." (PMID 38167704, 2024). "In chronic myeloid leukemia (CML), recombinant antibodies targeting IL-1 receptor antagonist (IL-1RA) and IL-1 receptor accessory protein (IL1RAP) can block IL-1 signaling in CML leukemia stem cells (LSCs) and inhibit their growth." (PMID 36761742, 2023). "Interleukin 1 receptor accessory protein (IL1RAP) is another candidate therapeutic target up-regulated on leukemia stem cells in myeloid malignancies." (PMID 31681270, 2019). "Expression of IL1RAP has been described in endometriosis and various leukemias, notably in leukemia stem cells, making IL1RAP a high-value target for EWS." (PMID 23251904, 2012). "As expected, genes associated with AML proliferation (FLT3, KIT), leukemia stem cells (CD34, CD38, and IL1RAP), and candidate genes overexpressed in AML (CD99, CD200, and LAMP2) were downregulated after chemotherapy, consistent with recent scRNA-Seq and immunohistochemistry data." (PMID 36099049, 2022). "Consistent with IL1RAP being up-regulated on leukemia stem cells vs. normal hematopoietic stem and progenitor cells, IL1RAP-targeting antibodies with enhanced CD16a-binding capacity induced selective NK cell-mediated ADCC when exposed to candidate leukemia stem cells." (PMID 31681270, 2019). "Anti IL1RAP/CD3 bispecific antibodies have demonstrated a high degree of specificity and IL1RAP targeting therapies are now going into first-in-human clinical trials (NCT02842320) in leukemias." (PMID 34521810, 2021). "Only a few markers, such as CLL-1 or interleukin-1 receptor accessory protein (IL-1RAP), may be more or less specific for LSC in certain human leukemia models." (PMID 25886184, 2015).
acute myeloid leukemia (8 papers, 2013 to 2025). Acute myeloid leukemia (AML) is a group of neoplasms arising from precursor cells committed to the myeloid cell-line differentiation. "High IL1RAP expression is associated with poor overall survival in acute myeloid leukemia (AML) patients; although several receptors genes were increased here, only IL18 genes were significantly up-regulated." (PMID 30061915, 2018). "IL1RAP has previously been shown to be overexpressed in acute myeloid leukemias (AML) and other myeloid malignancies." (PMID 38334625, 2024). "We present a proof of concept for a CAR T cell immunotherapy approach to targeting chronic myeloid leukemia (CML) or acute myeloid leukemia (AML) leukemic stem cells that express interleukin-1 receptor accessory protein (IL-1RAP)." (PMID 33414517, 2021). "In acute myeloid leukemia (AML) and CML, blocking IL-1 signaling (for example, with anti-IL-1RA or anti-IL1RAP antibodies, IRAK1/4 inhibitors, IL-11/4 inhibitors, AP antibodies) eliminates LSCs in the TME, thereby preventing recurrence in patients." (PMID 36761742, 2023). "The objective of this work was to reproduce this epitope-masking resistance model, in the context of acute myeloid leukemia (AML), based on our immunotherapeutic CAR T cell model targeting the accessory protein of the interleukin-1 receptor (IL-1RAP) expressed by leukemic stem cells." (PMID 33414517, 2021). "IL1RAP has been identified previously as a putative therapeutic stem cell-specific target in CML, as well as in acute myeloid leukemia (AML) and myelodysplastic syndrome (MDS) patients, with high expression correlating with poor overall survival in AML." (PMID 23651669, 2013).
pancreatic cancer (8 papers, 2021 to 2025). "In pancreatic cancer, IL1RAP promotes the activation of tumor-associated fibroblasts and immunosuppressive cells (e.g., MDSCs, Tregs), fostering an immunosuppressive microenvironment through the activation of the IL-1 signalling pathway." (PMID 40444099, 2025). "Another recent study showed that IL1RAP overexpression was associated with worse overall survival in pancreatic cancer patients, which was attributed to its facilitation of tumor cell viability, invasiveness, and clonogenic growth." (PMID 39218967, 2024). "In the context of advanced pancreatic cancer, IL1RAP has been recognized as a key mediator of innate immunity." (PMID 40444099, 2025). "It has also been shown that IL1RAP contributes to chemoresistance in pancreatic cancer cells, such as resistance to gemcitabine, by activating NF-κB and STAT3 signalling pathways." (PMID 40444099, 2025). "IL1RAP knockdown significantly reduced cell viability, invasiveness, and clonogenic growth in pancreatic cancer cell lines." (PMID 35606824, 2022). "IL-1RAcP has also been implicated in tumor progression in solid tumors and an anti-IL1RAP antibody (nadunolimab, CAN04) is in phase II clinical studies in pancreatic cancer and non-small cell lung cancer (NCT03267316)." (PMID 35003094, 2021). "Moreover, IL1RAP enhances the migration and invasion of pancreatic cancer cells by inducing epithelial-mesenchymal transition." (PMID 40444099, 2025). "We identified 7 highly expressed pancreatic cancer cell surface receptors (MET, NPR3, IL1RAP, SLC2A1, SLC6A6, GABRP, and TMPRSS4) in all the analyzed datasets." (PMID 35359382, 2022). "Overexpressed pancreatic cancer receptors include SLC2A1, MET, IL1RAP, NPR3, GABRP, SLC6A6, and TMPRSS4." (PMID 35359382, 2022). "The L5 proteins of 3 serotypes of adenovirus HAdV2, HAdV3, and HAdV5 are docked with the seven highly expressed pancreatic cancer receptors SLC2A1, MET, IL1RAP, NPR3, GABRP, SLC6A6, and TMPRSS4." (PMID 35359382, 2022).
Obesity (7 papers, 2017 to 2025). Accumulation of substantial excess body fat. "Carriers of 2KB upstream variant rs9990107 A and intron variant rs3836449 delCAGGGTGCCCCT (in the IL1RAP gene) are at a higher obesity risk." (PMID 34834553, 2021). "Two IL1RAP variants—rs9990107 A in a 2KB upstream region and rs3836449 delCAGGGTGCCCCT in an intron—are associated with a higher obesity risk in a Korean population." (PMID 34834553, 2021). "The soluble form of IL1RAP was shown to have antiinflammatory properties in blood, and multiple polymorphisms of IL1RAP have been linked to the development of inflammatory-related disorders such as obesity." (PMID 39589852, 2024). "The largest network included 20 proteins and was predicted to be involved in tissue morphology, inflammatory response and cardiovascular diseases including proteins encoded by genes already associated with obesity (INS, LEP, SERPINE1, IL1RAP, and RARRES2)." (PMID 29234017, 2017). "Additionally, proteins such as the SERPIN family and IL1RAP, identified in the hypertension model, link adiposome cargo to coagulation and interleukin signaling, two key pathways known to be dysregulated in obesity-related hypertension." (PMID 40981199, 2025). "Collectively, our data suggest that the miR-221-3p/222-3p cluster could potentially regulate AT functionality through the modulation of DVL2, ETS1, and IL1RAP during obesity and T2D." (PMID 38139277, 2023). "Additionally, the binding site prediction analysis further supported the direct regulation of miR-221-3p and miR-222-3p in the gene regulatory networks of ETS1, DVL2, and IL1RAP concerning obesity and T2D." (PMID 38139277, 2023). "Taken together, these findings indicated that in the presence of sex, obesity, and T2D, the expression levels of DVL2, ETS1, and IL1RAP are dependent on the type of AT depot." (PMID 38139277, 2023). "This enabled us to pinpoint 3 significant common target genes (ETS1, DVL2, and IL1RAP) exhibiting markedly distinct expression profiles in both VAT and SAT among patients with obesity and T2D." (PMID 38139277, 2023).
Ewing sarcoma (6 papers, 2021 to 2025). A small round cell tumor that lacks morphologic, immunohistochemical, and electron microscopic evidence of neuroectodermal differentiation. "Human anti-IL1RAP antibodies are able to induce potent antibody-dependent cellular cytotoxicity against Ewing sarcoma cells; for this reason, IL1RAP expression has gained attention from an immunotherapeutic perspective." (PMID 38334625, 2024). "Upon entering the circulation, Ewing sarcoma cells overcome anoikis by upregulating IL-1 receptor accessory protein (IL1RAP) enabling metastatic spread." (PMID 34831167, 2021). "Finally, it was demonstrated that the oncogenic EWS-ETS fusion proteins produced by Ewing sarcoma cells are the effectors of the transcriptional activation of IL-1RAP, resulting in IL-1RAP overexpression." (PMID 36499246, 2022). "A more recent surfaceome analyses revealed many new Ewing sarcoma cell surface targets including ENPP1 and CDH11 in addition to known IL1RAP, STEAP1, ADGRG2 and CD99, providing newer cell surface targets for immunotherapeutic application in Ewing sarcoma." (PMID 40442778, 2025). "IL1RAP overexpression has been described in hematological cancers such as CML and AML, as well as in solid tumors such as pancreatic ductal adenocarcinoma, Ewing sarcoma, glioma, triple negative breast cancer, non-small cell lung cancer, stomach adenocarcinoma, or cervical cancer." (PMID 40229904, 2025).
asthma (5 papers, 2021 to 2025). "In a previous study, the expression of IL1RAP mRNA in sputum was significantly associated with sputum neutrophilia and airflow obstruction in asthma." (PMID 35986608, 2023). "IL1RAP mRNA is increased in PBMCs from children with asthma compared with healthy controls, and its expression is enhanced with increasing asthma severity and during exacerbations." (PMID 35986608, 2023). "IL‐33‐activated gene signatures are elevated in neutrophilic and mixed granulocytic asthma corresponding with IL1RAP co‐receptor expression." (PMID 35986608, 2023). "IL1RAP mRNA expression was highest in severe neutrophilic and mixed granulocytic asthma." (PMID 35986608, 2023). "The mRNA expression for IL1RAP, the IL1RL1 co‐receptor, was greatest in severe neutrophilic and mixed granulocytic asthma." (PMID 35986608, 2023). "SMR results suggested that therapies targeting FPR1, IL1RAP, IL7R, and IL18RAP inflammatory variables may be able to prevent an increase in AD in moderate to severe asthma." (PMID 40951943, 2025). "IL1RL1 and IL1RAP mRNA expression was not differentiated amongst asthma cohorts in blood but IL1RL1 was elevated in the sputum of severe eosinophilic asthma." (PMID 35986608, 2023). "Alfa-1-antitrypsin (SERPIN1A) and IL1RAP were elevated only in asthma patients with high LCI, as opposed to IgM, CD93 and CCL18 which were elevated also in asthma patients without small airway involvement." (PMID 35668386, 2022). "Among these targets, FPR1 (Formyl Peptide Receptor 1), IL1RAP (Interleukin 1 Receptor Accessory Protein), IL7R (Interleukin 7 Receptor), and IL18RAP (Interleukin 18 Receptor Accessory Protein) warrant additional exploration as potential therapeutic targets for AD and moderate to severe asthma." (PMID 40951943, 2025).
COVID-19 (5 papers, 2021 to 2024). A disease caused by infection with severe acute respiratory syndrome coronavirus 2. "Albeit to a lesser extent, IL-1RAP, OASL and MX1 genes, which belong to the “senescence associated secretory phenotype” (SASP), were also found significantly upregulated in acute COVID-19 vs. HC monocytes." (PMID 34572439, 2021). "We found an SASP including IL1RAP, OASL and MX1 genes significantly upregulated in acute COVID-19." (PMID 34572439, 2021).
Alzheimer disease (4 papers, 2019 to 2025). A progressive, neurodegenerative disease characterized by loss of function and death of nerve cells in several areas of the brain leading to loss of cognitive function such as memory and language. "A possible involvement of the gene IL1RAP (interleukin-1 receptor-associated protein) in the pathogenesis of Alzheimer’s disease (AD) has been suggested in GWASs of cerebrospinal fluid (CSF) tau levels and longitudinal change in brain amyloid burden." (PMID 30792413, 2019). "Among the differentially expressed proteins, there were proteins involved either in the neurogenic process (e.g. GDF11) or in Alzheimer’s disease (e.g. LRRK2, RCAN1, NTRK2), or in both neurogenesis and Alzheimer’s disease (e.g. CREBBP, SFRP1, IL1RAP)." (PMID 36703180, 2023).
breast carcinoma (4 papers, 2016 to 2026). "Initial bioinformatics analysis of public databases revealed a significant correlation between elevated IL1RAP expression in macrophages and signatures of immune suppression and poor prognosis in breast cancer." (PMID 41752029, 2026). "Despite this, the importance of the expression of these genes in breast cancer is such that high IL1R1 or IL1RAP is strongly related to patient survival." (PMID 39201290, 2024). "Finally, the importance of the expression of these genes in breast cancer is such that high IL1R1 or IL1RAP is strongly related to patient survival." (PMID 39201290, 2024). "On the other hand, the macrophage infiltration showed a positive correlation with IL1R1, IL1RAP, and IL6ST gene expression in all subtypes of patients with breast cancer." (PMID 39201290, 2024). "Neutrophil infiltration had a direct relationship with the expression of IL1R1, IL1RN, IL1RAP, IL6ST, CXCL3, CXCL5, and CXCL6 in most of the subtypes of the breast cancer patients analyzed." (PMID 39201290, 2024).